PPARG (peroxisome proliferator activated receptor gamma)
Diseases named in the same sentence as PPARG in open-access papers (continued):
Sharing a sentence is not in itself a finding about the gene and the disease.
Hypertension (157 papers, 2005 to 2025). The presence of chronic increased pressure in the systemic arterial system. "In total, 59,5% of patients experience hypertension, with a higher percentage of patients affected among those with a PPARG variant in the DBD (63,8%) compared to those with a variant in the LDB (54,0%)." (PMID 39398333, 2024). "Initially, two cases of distinct mutations in the PPARG gene (Val318Met and Pro495Leu) were described with severe and difficult-to-control arterial hypertension, which appeared around 30 years of age." (PMID 39398333, 2024). "On the other hand, treatment with T0070907, an antagonist of PPARγ, in mice has been shown to induce hallmark symptoms of PE, including hypertension, proteinuria, and fetal growth restriction." (PMID 37299422, 2023). "Angiotensin II-induced endothelial dysfunction in adult offspring of pregnancy complicated with hypertension is associated with impaired endothelial PPARγ." (PMID 36359869, 2022). "Both rs1801133 mutation on Methylenetetrahydrofolate reductase (MTHFR) gene and transcription factor peroxisome proliferator-activated gamma (PPARG) have been associated with plasma homocysteine (Hcy) levels and hypertension." (PMID 35356087, 2022). "The composed pathway demonstrated the possible linkage among rs1801133 mutation, PPARG, homocysteine, folate, enalapril, hyperhomocysteinemia, and hypertension." (PMID 35356087, 2022). "High blood pressure is frequent, and can be very severe, in particular in partial lipodystrophies associated with pathogenic variants of PPARG encoding the adipogenic factor PPARγ (peroxisome proliferator-activated receptor gamma)." (PMID 35046902, 2021). "Main characteristics of studies involved in this meta-analysis of the PPARG Pro12Ala polymorphism and essential hypertension risk." (PMID 28727849, 2017). "Main characteristics of studies involved in this meta-analysis of the PPARG C161T polymorphism and essential hypertension risk." (PMID 28727849, 2017). "The homozygous P465L PPARγ mutation is lethal, but the heterozygous animals display hypertension and altered adipose tissue distribution similarly to human phenotypes." (PMID 27483259, 2016). "Novel mutations in PPARγ (R165T and L339X) linked to FPLD3 are associated with a defective transrepression of cellular RAS leading to cellular dysfunction, contributing to the specific FPLD3-linked severe hypertension." (PMID 27483259, 2016). "Recently, L-carnitine was also shown to reduce hypertension-associated renal fibrosis in a PPARγ-dependent manner." (PMID 27171144, 2016). "L-carnitine possesses antioxidative and antiinflammatory effects and reduced hypertension-associated renal fibrosis in a PPARγ-dependent manner." (PMID 27171144, 2016). "In vascular muscle, PPARγ interference causes hypertension under baseline conditions and dysfunction of both conduit and resistance blood vessels." (PMID 25122005, 2014). "Another study in Japanese showed that PPARG C-681G (rs10865710) polymorphism was significantly associated with the risk of CKD among subjects with hypertension, suggesting the biological roles of PPARs in the genesis of CKD also in Asian populations." (PMID 24288525, 2013). "In humans, both the Pro12Ala polymorphism and mutations in the PPARγ gene contribute to hypertension." (PMID 20613959, 2010). "Rare and natural PPARγ mutations have been associated with insulin resistance, hypertension, and vascular hypertrophy, with the majority of mutations reported to date found in the ligand-binding domain (LBD) of the receptor." (PMID 20300579, 2009). "In this sample of apparently healthy men, the prevalence of hypertension was low (~18%) and the impact of the PPARG-681G, -689T, and Ala12 alleles on blood pressure was clinically limited." (PMID 20016803, 2009). "Hypertension could be a risk for peroxisome proliferator-activated receptor-gamma (PPAR-γ) rs1801282 mutation in CAD subjects." (PMID 39759113, 2025).
Hypertension (continued). "Increased AT1R expression, which may cause hypertension through ROS and inflammation, is brought on by PPARγ mutations." (PMID 37189789, 2023). "However, in hypertension caused by smooth muscle–specific, dominant-negative PPARγ mutation, RhoBTB1 reversed hypertension by improving vasodilation." (PMID 35358093, 2022). "PPARG mutations cause hypertension in humans, and RhoBTB1 has been associated with BP." (PMID 35358093, 2022). "Specifically, it showed that rs1801133 mutation could promote plasma homocysteine and inhibit folate, which led to decreased PPARG expression and increased risk of hypertension and hyperhomocysteinemia." (PMID 35356087, 2022). "We recently showed that restoring Rhobtb1 expression in vascular SMCs in mice with SMC-specific, dominant-negative PPARγ reversed the hypertension, vascular dysfunction, and arterial stiffness caused by the smooth muscle–specific expression of a dominant-negative mutation of PPARγ." (PMID 35358093, 2022). "Pathway analysis showed that T-allele of rs1801133 could inhibit the expression of PPARG through the downregulation of folate levels and upregulation of Hcy levels, which increased the risk of hypertension and hyperhomocysteinemia." (PMID 35356087, 2022). "Summary of meta-analysis of association of the PPARG polymorphisms and essential hypertension risk." (PMID 28727849, 2017). "Furthermore, mice with a dominant-negative point mutation in PPARγ (P465L) developed significantly more severe cardiac fibrosis to Ang II-induced hypertension." (PMID 27293418, 2016). "Thus, these mice faithfully phenocopy the hypertension portion of the overall phenotype exhibited by patients with identical PPARγ mutations." (PMID 25122005, 2014). "This suggests that the loss of PPARγ signaling in smooth muscle may be sufficient to phenocopy the hypertension that results from the presence of the mutation in all cells in human patients." (PMID 25122005, 2014). "Dysregulation in the PPARγ activity may underlie diseases connected with the metabolic syndrome and hypertension." (PMID 24454335, 2013). "In addition, the Pro12Ala polymorphism and mutations in the PPARγ gene are associated with hypertension in humans." (PMID 22448165, 2012). "According to studies, hypertension risk may be increased by polymorphisms in the PPARG gene." (PMID 37571339, 2023). "Moreover, the novel PPARγ mutations Arg165Thr and Leu339X, which are linked to familial partial lipodystrophies, are associated with a defective transrepression of RAS, leading to cellular dysfunction and contributing to the specific FPLD3-linked severe hypertension." (PMID 30012954, 2018). "In vitro experiments confirmed that (P)RR plays a role between hypertension and MAFLD and that inhibiting (P)RR expression can improve hypertension combined with MAFLD via the ERK/PPARγ pathway." (PMID 40650317, 2025). "To further investigate the role of the (P)RR/ERK/PPARγ pathway in the development of hypertension combined with MAFLD, we used the (P)RR antagonist HRP for the specific inhibition of (P)RR." (PMID 40650317, 2025). "This study first reveals the molecular mechanism by which the (P)RR/ERK/PPARγ pathway participates in the development of hypertension combined with MAFLD, providing support for the development of future therapeutic drugs for hypertension combined with MAFLD." (PMID 40650317, 2025). "Overexpression of Cathepsin K in kidney mesangial cells indirectly increases peroxisome proliferator-activated receptor-gamma-caspase-8-mediated cell apoptosis, kidney remodelling and hypertension." (PMID 41325840, 2025). "The differences in PPARα activity driven by sex hormones contrast with the PPARγ activity that appears to have a similar effect on hypertension in both sexes in mice." (PMID 40829644, 2025). "Activated peroxisome proliferator-activated receptor gamma (PPARγ) acts as a dilating agent, regulating hypertension and stimulates adipogenesis to prevent plaque formation." (PMID 40943067, 2025).
Hypertension (continued). "And we found the (P)RR/ERK/PPARγ axis for the first time, which plays an important role in the progression of spontaneous hypertension combined with MAFLD." (PMID 40650317, 2025). "Another study offered similar evidence by showing that a combination of low doses of PPARα (fenofibrate) and PPARγ (rosiglitazone) activators reduced the hypertension development in the model of Ang II–infused Sprague–Dawley rats." (PMID 40137963, 2025). "A study based on spontaneously hypertensive rats revealed a possible mechanism of hypertension‐related kidney injury: hypertension resulted in the downregulation of PPARγ and subsequent upregulation of GRK2, which impaired renal vascular reactivity." (PMID 39438268, 2024). "RBP7 is a PPARγ (peroxisome proliferator-activated receptor γ) target gene and forms a positive feedback loop with PPARγ in hypertensive diseases." (PMID 38553715, 2024). "Treatment of RUPP rats with rosiglitazone, a PPARγ agonist, has been shown to ameliorate hypertension, improve vasorelaxation, and reduce ACR." (PMID 37299422, 2023). "Currently, no information exists with regard to the reprogramming effect of PPARβ/δ on programmed hypertension, despite PPARγ modulators having been considered attractive drug targets for addressing metabolic disorders." (PMID 36984857, 2023). "Pregnant female rats show PE symptoms, such as arterial hypertension, proteinuria, and fetal growth retardation, when treated with a PPARγ antagonist." (PMID 38003402, 2023). "Selective PPARγ agonists, pioglitazone and rosiglitazone, can be protective in low protein diet-induced hypertension and genetic hypertension." (PMID 36984857, 2023). "A multitargeted interaction-based degree algorithm and a phylogenetic tree of pathways showed that the NR3C1, REN, PPARG, and CYP11B1 hub genes were consistently modulated by Υ-sitosterol to reduce hypertension and related risk factors." (PMID 37571339, 2023). "Maternal HFD-induced offspring hypertension is correlated to inhibitory AMP-activated protein kinase (AMPK)/peroxisome proliferator-activated receptor-γ (PPARγ) coactivator-1α (PGC-1α) pathway in offspring kidneys." (PMID 35897755, 2022). "In mice, interference with PPARγ signaling in vascular SMCs results in hypertension, vascular dysfunction, and arterial stiffness; furthermore, Rhobtb1 expression decreases concurrently with these phenotypes." (PMID 35358093, 2022). "CTRP6 alleviates AngII-induced hypertension and vascular endothelial dysfunction in spontaneously hypertensive rats through activating PPARγ." (PMID 35379352, 2022). "Rosiglitazone, a peroxisome proliferator activator receptor gamma (PPARγ) agonist, targets adipose tissue and has been shown to reduce endothelin-1 and attenuate hypertension as well as renal inflammation and injury in SLE mice model." (PMID 35770194, 2022). "PGC-1α binds to PPARγ and coactivates PPARγ to facilitate the expression of specific sets of PPAR target genes participating in hypertension." (PMID 35897755, 2022). "The transcription factor PPARγ also modulates insulin sensitivity and hypertension through its anti-inflammatory and vasodilatory actions." (PMID 34966295, 2021). "We investigated the possible modulatory effect of PPARγ activation on the vascular effects of ET-1 in hypertension." (PMID 31712626, 2019). "PPARγ as a nutrient-sensing signal can influence developmental programming of hypertension either directly through PPAR target genes or indirectly through Nrf2 activation." (PMID 29636848, 2018). "In recent years, decreased PPARG levels have been reported in subjects with high blood pressure not only in vitro but also in vivo." (PMID 28727849, 2017). "In rats with L-NAME induced hypertension, treatment with L-carnitine normalizes hypertension, hypertrophy, fibrosis, PPARγ expression, and expression of fibrotic factors." (PMID 26713088, 2015).
Hypertension (continued). "A subgroup of ARBs can act as a partial agonist of PPARγ, which are protective in both genetic and acquired animal models of hypertension." (PMID 26712739, 2015). "On the other hand, selective PPARγ agonists, rosiglitazone and pioglitazone, can be protective in both spontaneously hypertensive rats (SHRs) and developmentally-programmed hypertension." (PMID 26712739, 2015). "The effects of PPARγ in the vascular cells indicate its beneficial function in vascular disorders including hypertension and atherosclerosis." (PMID 25302079, 2014). "It has been reported that vascular SMC PPARγ prevents the switch from a contractile to a proliferative state during vascular injury and hypertension." (PMID 25122005, 2014). "Telmisartan is an angiotensin I (AT1) receptor blocker used in the treatment of essential hypertension, with partial peroxisome proliferator-activated receptor γ (PPARγ) agonism." (PMID 25360175, 2014). "Several studies using RSG confirmed the blood pressure lowering effect of this PPARγ agonist in experimental hypertension." (PMID 24454335, 2013). "The mechanism of alleviation of hypertension-induced cognitive deficits by angiotensin receptor type 1 blockers (the sartans) most probably involves their ability to stimulate peroxisome proliferator-activated receptor gamma (PPAR-γ)." (PMID 22890474, 2013). "PPARγ are expressed in vascular SMCs, and interference with PPARγ in SMCs resulted in systemic hypertension in part due to attenuation of endothelium-dependent and independent vasodilation." (PMID 23888144, 2013). "In the present study, we investigated the effects of PPARγ agonist pioglitazone during hypertension development in young SHR." (PMID 24454335, 2013). "Despite this, experimental and clinical studies have demonstrated that PPARγ activation by TZDs commonly reduces blood pressure and prevents the development of hypertension." (PMID 22448165, 2012). "Modest decreases in blood pressure during treatment with PPARγ agonists are a consistent finding in studies conducted in normal, diabetic, and hypertension-prone rodents and humans." (PMID 20069049, 2010). "(P)RR was specifically blocked using handle region peptide (HRP), and Nile red fluorescence staining, (P)RR/ERK/PPARγ protein expression analysis, and immunofluorescence were performed to further verify the role of (P)RR in the pathogenesis of hypertension combined with MAFLD." (PMID 40650317, 2025). "It has been confirmed that (P)RR can promote the expression of downstream proteins related to fatty acid synthesis and transport, such as ACC-1, FAS, and CD36, by upregulating the expression of ERK/PPARγ, thereby inducing the occurrence of hypertension combined with MAFLD." (PMID 40650317, 2025). "PPAR polymorphisms may be responsible for the risk of being overweight or obese, whereas dominant-negative PPARγ mutations result in T2DM, hypertension, and IR." (PMID 37372966, 2023). "Many studies confirmed that PPARG plays a protective role in hypertension." (PMID 35356087, 2022). "Furthermore, CTRP6 overexpression was reported to activate the PPARγ signal to relieve hypertension and vascular endothelial dysfunction in spontaneously hypertensive rats." (PMID 34964705, 2022). "However, PPARG has been shown to play a protective role in hypertension and has been demonstrated to lower plasma homocysteine." (PMID 35356087, 2022). "However, activation of PPARγ has beneficial effects on hypertension in a number of animal and human studies." (PMID 36359869, 2022). "A lack of PPARγ leads to placental defects, an increase of proinflammatory cytokines is associated with hypertension." (PMID 34830351, 2021). "Indeed, telmisartan represses MCP-1 expression from peripheral monocytes in patients with essential hypertension and drives monocytes to M2 macrophage polarization in mice following stimulation of peroxisome proliferator-activated receptor gamma (PPAR-γ)." (PMID 34199409, 2021).
Hypertension (continued). "Other studies reported that by inhibiting M1 activation using Fenretinide, an anticancer agent that can perform anti-invasive and anti-metastatic functions, hypertension can be controlled in rat by activating the peroxisome proliferator-activated receptor gamma pathway." (PMID 33154752, 2020). "Dominant-negative PPARγ mutations are associated with severe IR, hypertension, and alterations in lipid profiles (low high-density lipoprotein [HDL], high TGs)." (PMID 28042289, 2016). "To address this shortcoming, we developed novel models expressing dominant negative mutations in PPARγ, the same mutations that cause hypertension in human patients, selectively in endothelium and vascular smooth muscle." (PMID 25122005, 2014). "However,recent studies have established that pulmonary hypertension in humans isassociated with reduced PPARγ expression andthat PPARγ ligands can attenuate the development ofpulmonary hypertension in several experimental models." (PMID 17710111, 2007). "Evidence from clinical studies and animal hypertension models have demonstrated that PPARα, PPARγ, and FXR agonism can lower blood pressure and decrease end organ damage which could be useful for the treatment of hypertension in patients with metabolic diseases." (PMID 37427406, 2023). "Therefore, as an inhibitor of hypertension and hyperhomocysteinemia, PPARG might also be involved in the treatment of H-type hypertension using EMFAT." (PMID 35356087, 2022). "The strongest evidence supporting a role for PPARγ in arterial pressure regulation comes from genetic studies where patients bearing rare dominant negative mutations in PPARγ exhibit severe early onset hypertension." (PMID 25122005, 2014). "In addition, treatment with the PPARγ activator rosiglitazone in a placental ischemia model of preeclampsia ameliorated hypertension in pregnant rats and improved mesenteric artery vasodilation, suggesting PPARγ as a potential therapeutic target in the treatment of preeclampsia." (PMID 23888144, 2013). "Thus, it may be possible that PPARγ activation reduces hypertension through reduction of homocysteine, at least in part." (PMID 20613990, 2010). "There are three PPAR subtypes—PPARα, PPARδ (also known as PPARβ), and PPARγ, which regulate gene expression in a variety of process, including lipid and glucose metabolism, atherosclerotic plaque formation, cellular differentiation, angiogenesis, inflammation, hypertension, and heart failure." (PMID 20613990, 2010). "Furthermore, recent work has shown that Irbesartan and Telmisartan act as partial peroxisome proliferator-activated receptor gamma (PPARγ) agonists at concentrations that are achievable with oral doses recommended for the treatment of hypertension, thus suggesting their insulin-sensitizing effect." (PMID 17407587, 2007). "The results show that LST-1 and LST-2 increased the PPARγ protein levels significantly compared to control and L-NAME-induced hypertension in rats." (PMID 40137963, 2025). "VST and VST/HCTZ liquisolid tablets inhibit AT1 receptor gene expression via activation of PPARγ and Nrf2 gene expression, as well as by inhibiting MAPK signaling pathways, including P38 and ERK kinases in the L-NAME-induced hypertension model." (PMID 40137963, 2025). "The downstream signaling of PGC-1α impacts PPARγ, which regulates the expression of particular PPAR target genes involved in hypertension with developmental origins." (PMID 39911806, 2025). "To clarify the intrinsic mechanisms of hypertension combined with MAFLD in SHRs and the relationship with the (P)RR/ERK/PPARγ pathway, we added HRP to specifically block (P)RR in in vitro experiments." (PMID 40650317, 2025). "In hypertension, the activation of the CTRP6/ERK/PPARγ axis can alleviate ANG II -induced endothelial dysfunction." (PMID 38994368, 2024). "In a maternal methyl-donor diet model, offspring hypertension coincided with the reduced renal expression of SIRT1, AMPKα2, PPARβ, and PPARγ." (PMID 37175813, 2023).